PDX1 (pancreatic and duodenal homeobox 1)
Diseases named in the same sentence as PDX1 in open-access papers (continued):
Sharing a sentence is not in itself a finding about the gene and the disease.
pancreatitis (17 papers, 2015 to 2026). Inflammation of the pancreas. "To confirm the enhanced tissue damage response during acute pancreatitis observed with loss of Ehmt2, we performed a pairwise analysis of the pancreatitis transcriptional landscape of the Ehmt2 knockout generated either with the Pdx1-Cre (Pdx1-Ehmt2fl/fl) or P48Cre/+ (P48-Ehmt2fl/fl) -driven models." (PMID 38948355, 2024). "Significant differences in macrophage infiltration and HO-1 expression were detected in LSL-KrasG12D/+; Pdx-1-Cre (KC) mice, Nrf2 whole-body knockout (KO) mice and wildtype mice with pancreatitis." (PMID 39337472, 2024). "We next focused on examining the expressional patterns of PAF1, YAP1, and TEAD1 in cerulein-induced wild-type (WT) and KrasG12D, Pdx-1 Cre (KC) pancreatitis mouse models." (PMID 36180487, 2022). "Moreover, deletion of miR-301a reduced the characteristic features of fibrosis in spontaneous and pancreatitis-accelerated PanIN formation in Pdx1-Cre;KrasG12D mice." (PMID 35211358, 2022). "We mainly used pancreatic acinar cell 3-dimensional (3D) culture and a spontaneous pancreatic precancerous lesion mouse model called LSL-KrasG12D/+; Pdx1-Cre (KC) (and pancreatitis models derived from KC mice) to explore the pro-tumorigenesis mechanisms of the HSF1 in vitro and in vivo." (PMID 33422093, 2021). "We examined whether other classical features of pancreatitis were also present in Pdx1-Cre;HIF2dPA postnatal pancreata." (PMID 30209343, 2018). "Furthermore, patient 36, who was homozygous for a PDX1 start‐loss variant, did not have symptoms of pancreatitis and/or malabsorption, but had intrahepatic biliary tract hypoplasia and died in infancy." (PMID 36398453, 2023). "Next the severity of AP in hM3/Pdx1 and hM3/BAC mice was compared with the commonly used cerulein-induced pancreatitis model." (PMID 34314386, 2021). "However, because Pdx1-Cre recombination occurs in the whole pancreas, including in islet, acinar, and even pancreatic stem cells, β cells’ malfunction results in higher insulin and reduced blood glucose levels, both of which may exacerbate pancreatitis." (PMID 34314386, 2021). "Furthermore, inflammation facilitates EMT, and an increase in the number of CPCs was observed in Pdx1-Cre; RosaYFP and Pdx1-Cre; KrasG12D; RosaYFP mouse pancreatitis models, to some degree, which could prove the significant role inflammation plays in the PDAC metastasis." (PMID 29379795, 2017). "Importantly, Pdx1‐Cre, Cxcr2fl/fl mice, in which Cxcr2 is deleted from pancreatic epithelial cells, were not protected from pancreatitis." (PMID 25950520, 2015).
pancreatic agenesis (13 papers, 2013 to 2025). Partial agenesis of the pancreas is characterized by the congenital absence of a critical mass of pancreatic tissue. "PDX1 is also implicated in pancreatic agenesis, usually arising from PDX1 mutations that truncate the protein product; PDX1 mutations have even been found in individuals with mutations in other MODY-linked genes." (PMID 36272648, 2022). "Recessive PDX1 (IPF1) mutations are a rare cause of pancreatic agenesis, with three cases reported worldwide." (PMID 23320570, 2013). "The first homozygous PDX1 mutation was reported in an infant with pancreatic agenesis 5, with a homozygous deletion of a single nucleotide, resulting in a premature termination codon (Pro63fsX60)." (PMID 23320570, 2013). "In humans, a recent study showed strong reduction of enteroendocrine cells in intestinal organoids differentiated from induced pluripotent stem cells collected from a patient with pancreatic agenesis and chronic diarrhoea caused by a homozygous p.(Pro63fs) PDX1 variant." (PMID 39542526, 2024). "Biallelic mutations in PDX1 are a known cause of pancreatic agenesis." (PMID 23320570, 2013). "So far, more than 30 cases of PDX1-MODY or pancreatic agenesis have been reported in peer-reviewed journals; however, clinical information remains limited." (PMID 40379627, 2025). "Several recent publications in which PDX1 was ablated resulted in pancreatic agenesis and have been employed as a means for facilitating organogenesis from donor embryos, paving the way for human stem cell or tissue specific stem cell mediated organogenesis." (PMID 29483633, 2018). "PDX1 is required for early embryonic development of the pancreas, as in human study a case report has shown a 5-year-old female Caucasian suffering from pancreatic agenesis because of a homozygous, single nucleotide deletion within the PDX1 gene." (PMID 29096722, 2017). "Biallelic PDX1 variants are a rare cause of isolated pancreatic agenesis and neonatal diabetes (NDM) without exocrine pancreatic insufficiency, with 17 cases reported in the literature." (PMID 39542526, 2024). "Naturally occurring non-functional mutations in the PDX1 gene have been reported in people born with pancreatic agenesis." (PMID 29383175, 2017). "Due to the decreased expression of transcription factors that promote endocrine function and pancreas development, PDX1, MAFA, and NKX6.1, pancreatic agenesis is present in 83.6%." (PMID 39596087, 2024).
pancreatic adenocarcinoma (11 papers, 2013 to 2025). "SHIP1 has been shown to be a promoter with higher activity than that of endogenous human insulin promoters and rat insulin promoters (RIP), which are used to direct expression in pancreatic adenocarcinoma that overexpresses pancreas and duodenal Homeobox gene 1 (PDX-1)." (PMID 33381459, 2020).
Obesity (10 papers, 2019 to 2026). Accumulation of substantial excess body fat. "Besides mouse models with DIO, a recent study showed that KC mice with genetic obesity (Pdx1-Cre;LSL-KrasG12D/+ mice crossed with leptin-deficient [ob/ob] mice) also developed PDAC faster and succumbed to the disease earlier." (PMID 34680216, 2021). "The pancreata of rats with diet-induced obesity showed a high expression of Pdx1 (P<0.05) together with low transcript levels of Wnt4 (P<0.05), without changes in Neurog3." (PMID 37274331, 2023). "Another significant gene-environment interaction in our study was between obesity and PDX1 rs9581943." (PMID 32456644, 2020). "Interestingly, rats with diet-induced obesity in the pair-fed group maintained high levels of Pdx1 and Neurog3, pointing to an increased formation of insulin-secreting β-cells." (PMID 37274331, 2023). "However, KC mice with genetic obesity (Pdx1-Cre;LSL-KrasG12D/+ mice crossed with ob/ob mice) that are leptin deficient also developed PDAC faster, arguing against a causative role of leptin in PDAC." (PMID 34680216, 2021). "Obesity decreases the GLP-1 cell lineage as evidenced by lower NKX2.2, PAX6, FOXA1, and PDX1 gene expression in (Ob + ObD) individuals compared to NOb individuals." (PMID 33037328, 2021).
Impaired glucose tolerance (9 papers, 2012 to 2025). An abnormal resistance to glucose, i.e., a reduction in the ability to maintain glucose levels in the blood stream within normal limits following oral or intravenous administration of glucose. "Impaired glucose tolerance enhances the downregulation of Pdx1, causing the miR-338 to be upregulated." (PMID 35328389, 2022). "MG101 with pre-GDM was positive for a reported E224K PDX1 mutation which was shown to result in reduced tranactivation and was also found to co-segregating with early-onset diabetes or impaired glucose tolerance in an Indo-Trinidadian family." (PMID 28095440, 2017). "This decreased Pdx1 and p-NeuroD1 expressions in this study was closely associated with reduced β-cell mass in the F2-HF, which led to an impaired glucose tolerance in early life." (PMID 29118817, 2017). "Furthermore, the patient’s brother, with impaired glucose tolerance but regular potassium levels, also bore this mutation, hinting at additional impacts of the PDX1 gene mutation on glucose metabolism regulation beyond the known impacts of GS." (PMID 38333726, 2023). "Interestingly, her mother who is a carrier of this PDX1 E224K has impaired glucose tolerance." (PMID 28095440, 2017).
gastric cancer (8 papers, 2017 to 2024). A primary or metastatic malignant neoplasm involving the stomach. "ING5 deletion in parietal, stem-like, and Pdx1-positive cells of gastric epithelium might contribute to the histogenesis of gastric cancer, and increase the susceptibility to chemically induced gastric carcinogenesis." (PMID 35747809, 2022). "PDX1 is a well-established tumor suppressor gene with down-regulated expression in patients with gastric cancer." (PMID 38356808, 2024). "While screening gastric cancer cell lines, PDX‐1 and PDXO‐1, we focused on GSDMB, and in subsequent knockdown experiments, we confirmed that the pyroptosis and antitumor effects of IBI315‐mediated T cells were dependent on GSDMB." (PMID 37587833, 2023). "PDX1 is a TF of homeobox genes family important in differentiation and development of the pancreas, duodenum and antrum, which functions as a putative tumor suppressor in gastric cancer." (PMID 32850701, 2020). "PDX1 is often expressed in normal gastric glands but is absent in human gastric cancer cell lines and gastric cancer." (PMID 28512631, 2017).
breast cancer (7 papers, 2011 to 2022). A primary or metastatic malignant neoplasm involving the breast. "To further verify the identified target genes that showed significant changes in DE and DM patterns in response to the combination treatment, we evaluated the expression of Pdx1, Tmem132d, Get4, Rpl13 and Ndufa1 genes in mouse mammary tumors using qRT-PCR." (PMID 33947955, 2021).
colorectal cancer (7 papers, 2014 to 2025). A primary or metastatic malignant neoplasm that affects the colon or rectum. "Another study in colorectal cancer demonstrated tumor specific DNA methylation of CpG islands located in 3′ exons was associated with up-regulation of IPF1/PDX1 and OTX1 gene expression." (PMID 25682867, 2015). "In total, 150 genes were inferred as methylation-regulated genes (MRGs) across the total colorectal cancer cohort, with two genes in particular—PDX1 and GNG7—consistently identified in both rectal and colon cancer individual analyses." (PMID 40565513, 2025). "Among the syntenic blocks between these regions, CDX2, CDK8, GSX1, and PDX1 are among candidate colorectal carcinoma and/or cancer driver genes affected by these recurrently gained chrs between human and mouse." (PMID 41051921, 2025). "For example, PDX1, a potential tumor marker in colorectal cancer, contains both a lost repressive SCRE (‘Pair_18_SCRE66’) and a gained active SCRE (‘Pair_10_SCRE127’, a super-enhancer cataloged in Reference) in colorectal cancer." (PMID 38213995, 2024). "A total of 150 genes were identified as MRGs from CRC analysis which includes PDX1 and GNG7 as spotlight genes were consistently found in rectal as well as colorectal cancer samples in both differentially expressed and methylated gene groups." (PMID 40565513, 2025). "Among the regulons driving classical states were those driven by TBX10, PDX1, FOXA3 and CDX2, which is a known prognostic marker in gastrointestinal cancers, especially colorectal cancer, and has been described as a lineage survival oncogene." (PMID 39417106, 2024).
Hyperinsulinemia (7 papers, 2012 to 2022). An increased concentration of insulin in the blood. "Notably, LDL treatment increased mRNA levels and insulin secretion; this hyperinsulinism condition was associated with the transcription factor PDX-1." (PMID 36005626, 2022). "Cholesterol should be the regulatory factor that induces the expression of the PDX-1, impacting hyperinsulinemia." (PMID 36005626, 2022). "Systemically delivered NICD shRNA suppressed islet expression of PDX-1 and reversed the hypoglycemia and hyperinsulinemia." (PMID 24705209, 2013). "Indeed, it was found that the H3 and H4 histones in the proximal promoter region of the insulin gene transcription factor, pancreatic duodenal homeobox-1 (PDX1), were hyperacetylated, ultimately leading to hyperinsulinemia." (PMID 26861388, 2016). "Systemically-delivered NICD shRNA reversed the enhancing effect of NICD on PDX-1, as well as on hyperinsulinemia and hypoglycemia, suggesting that Notch1 could be a potential therapeutic target." (PMID 24705209, 2013). "Thus, overt hyperinsulinemia does not appear to cause hypoglycemia in Pdx-1-Creearly;VhlhLoxP/LoxP pups." (PMID 23977255, 2013). "Given the role of PDX1 in β-cell replication, and elevated fetal INS expression, these alterations in expression in response to d62 MI-TP may therefore represent fetal antecedents of the increased β-cell numbers and hyperinsulinemia observed in offspring from MI-TP manipulated pregnancies." (PMID 23457541, 2013).
Hypoglycemia (7 papers, 2012 to 2025). A decreased concentration of glucose in the blood. "Severe hypoglycemia appears to be the primary cause of death in Pdx-1-Creearly;VhlhLoxP/LoxP (and Rfx6-Cre;VhlhLoxP/LoxP and Ngn3-Cre;VhlhLoxP/LoxP) pups." (PMID 23977255, 2013). "Nevertheless, we cannot formally rule out that a combined perturbation in α- and ß-cell function may cause the hypoglycemia observed in Pdx-1-Creearly;VhlhLoxP/LoxP mice." (PMID 23977255, 2013). "The results of this study suggest that neonatal hypoglycemia may be related to the decreased expression levels of PDX1, NGN3 and Pax6 genes in pregnant women with GDM." (PMID 38356808, 2024). "Changes in maternal PDX1 methylation, NGN3 and Pax6 expression levels may lead to abnormal glucose metabolism in neonates, which has a close bearing on neonatal hypoglycemia and blood glucose levels caused by GDM." (PMID 38356808, 2024). "Summarily, our results indicate that secretion of glucagon is impaired in islets lacking Vhlh and suggest a likely mechanism for the hypoglycemia in Pdx-1-Creearly;VhlhLoxP/LoxP, Ngn3-Cre;VhlhLoxP/LoxP and Rfx6;VhlhLoxP/LoxP mice." (PMID 23977255, 2013). "Thus, intestinal expression of Pdx1, MafA, and Ngn3 drives the formation of ectopic insulin-producing cells that confer an improved response to glucose challenge without fasting hypoglycemia." (PMID 24613355, 2014).
maturity-onset diabetes of the young type 4 (7 papers, 2010 to 2026). Monogenic diabetes caused by inactivating mutation(s) in the PDX1 gene, encoding pancreas/duodenum homeobox protein 1. "Deficiencies in pdx1 (MODY type 4) and hnf1bMODY type 5 might be expected to have the most severe effect on insulin production due to the direct feedback by insulin on gene expression or protein activity." (PMID 20587063, 2010). "Mutation in PDX-1 causes autosomal forms of early-onset diabetes (maturity-onset diabetes of the young type 4 [MODY4])." (PMID 26082830, 2015).
metastatic tumors (7 papers, 2010 to 2025). "In parallel, we also performed a functional screen on primary cells from Pdx1-Cre KrasG12Dp53R172H (KPC) metastatic tumors." (PMID 26077591, 2015). "These LSL-KrasG12D;Ink4a/Arfflox/flox;Pdx1-Cre mice presented with invasive, metastatic disease consistent with human disease." (PMID 25538623, 2014). "All metastatic tumors expressed ARX, two also expressed PDX1 (double positive)." (PMID 31846235, 2020). "Additionally, IPMN-like lesions accompanied by PDAC and metastatic disease were shown with the LSL-KrasG12D/+;Smad4flox/flox;Pdx1-Cre model." (PMID 25538623, 2014). "Of note, no basal cell carcinomas (BCC) were observed in Pdx1-Cre;Kras;N1ko mice and no signs of a metastatic disease were observed." (PMID 21042537, 2010).
pancreatic disease (7 papers, 2009 to 2022). "Combining emerging evidence with previously published findings, we suggest a mechanism for the relationship between BLK, the PDX1 transcription factor, and pancreatic disease." (PMID 33233470, 2020). "Together, these findings support the development of a phase I clinical trial using this novel RNAi platform targeting PDX-1 for treating this devastating pancreatic disease." (PMID 22905092, 2012). "Additionally, our data provide increased understanding of the relationship between BLK protein tyrosine kinase, PDX1 transcription factor, and pancreatic disease." (PMID 33213062, 2020). "Most significantly, we presented the first mouse model of VHL-associated pancreatic disease in mice lacking pVHL utilizing Pdx1-Cre transgenic mice to inactivate Vhl in pancreatic progenitor cells." (PMID 19340311, 2009).